SERPINB5 (serpin family B member 5)
Diseases named in the same sentence as SERPINB5 in open-access papers (continued):
Sharing a sentence is not in itself a finding about the gene and the disease.
tumor (continued). "SERPINB5/maspin is a putative tumor suppressors, through influence on cell-matrix interactions." (PMID 30473748, 2018). "SERPINB5 has been identified as a type II tumor suppressor gene in normal mammary epithelial cells by subtractive hybridization, and is located on human chromosome 18q21.3-q23 along with other serpin genes, such as squamous cell carcinoma antigens 1 and 2, PAI-2 and headpin." (PMID 29029529, 2017). "Finally, an additional integrated in silico analysis confirmed that these SNPs affected SERPINB5 expression and protein stability, which significantly correlated with tumour expression and subsequently with tumour development and aggressiveness." (PMID 27221742, 2016). "Analysis of a number of other genes that are strongly and specifically expressed in tumour over normal lung, including SERPINB5, TERT and PRAME, showed marked allelic expression imbalances in the tumour tissue in the context of balanced or only marginally imbalanced relative allelic copy numbers." (PMID 16222316, 2005). "In addition, SERPINB5 mutation completely blocked the radioresistant effect of TRIM21, suggesting that TRIM21 acts through SERPINB5 to manipulate tumor cell radiosensitivity." (PMID 32005234, 2020). "Moreover, Serpins display functions such as blood pressure regulation (SERPINA8), hormone transport (SERPINA6, SERPINA7), tumor suppression (SERPINB5) (Zhang, Magit & Sager, 1997) as well as molecular chaperone functions (SERPINH1) which are not based on protease inhibition." (PMID 31531264, 2019). "Both AEI and AI were measured in a series of informative patients using mRNA-encoded cSNPs for SERPINB5 (encoding maspin), TERT (encoding a telomerase subunit) and PRAME (encoding a tumour antigen of unknown function with a highly restricted normal tissue expression pattern." (PMID 16222316, 2005). "SERPINB5, SFRP1, and TFRC showed elevated expression levels in PAAD tumor samples compared to normal samples." (PMID 41595468, 2025). "SERPINB5, SFRP1, and TFRC exhibited higher expression levels in PAAD tumor samples, consistent with the gene expression data from the HPA database." (PMID 41595468, 2025). "The results of our study showed that when BTG2 was low expression and SerpinB5 was high expression in LUAD, the macrophage M0 in the tumor microenvironment increases during tumorigenesis." (PMID 37006240, 2023). "Enrichment analysis showed four differential expression genes (DEGs) related to tumor growth pathways RASAL2, SerpinB5, UTG1A4, and PDE3A." (PMID 36159573, 2022). "ITGA8 and ADAMTS8 were downregulated in tumor tissues, whereas FERMT1, CTSV, CPS1, ENTPD2, SERPINB5, and LYPD3 were upregulated in tumor tissues." (PMID 35557945, 2022). "More importantly, the authors identified upregulation of MASPIN/SERPINB5, a tumor suppressor gene for UM, as well as downregulation of proteins related to angiogenesis, such as HIF-1α and VEGF, as cause of AEZS-108 efficacy." (PMID 33964953, 2021). "Based on the RNA-seq data, we observed that genes that suppress tumor angiogenesis, including SERPINE1, THBS1, SERPINB5, CD82 and ANGPTL4, were upregulated." (PMID 32106543, 2020). "Another meta-analysis approach based on PDAC datasets allowed the identification of a 5 genes classifier signature (TMPRSS4, AHNAK2, POSTN, ECT2, SERPINB5) with 95% sensitivity and 89% specificity in discriminating PDAC from non-tumor samples." (PMID 30236127, 2018). "The tumor progression reduced by hsa-miR-21 down-regulation is mediated by the hsa-miR-21 target genes; the target genes are metastasis-related tumor suppressor genes such as TPM1, Programmed Cell Death 4 (PDCD4) and SERPINB5." (PMID 28793339, 2017).
tumor (continued). "Other tumor suppressors, such as Dipeptidyl peptidase 4 (DPPIV), Pigment epithelium-derived factor (PEDF) and SerpinB5 were also upregulated in the secretome of T24shPFN1 cells, (30.3, 13.6 and 9.7-fold, respectively)." (PMID 27683119, 2016). "For SERPINB5, AEI was seen in 15 out of 25 (60%) of informative tumours, 11 of which showed a phase-matched allelic imbalance." (PMID 16222316, 2005). "A number of genes have recently been shown to be expressed strongly in tumours, preneoplastic bronchial lesions and in the normal multipotent basal epithelial cells of the airway: examples include S100A2, TP73L and SERPINB5." (PMID 15467767, 2004). "Notably, CALU, TFRC, and GBP2 were highly expressed in early developmental stages, whereas SERPINB5 and LY6D were up-regulated in later phases, indicating their involvement in distinct stages of cellular state transitions and tumor progression." (PMID 41595468, 2025). "It has been shown previously that non-inhibitory serpins such as SerpinB5/Maspin can lead to an increase in the sensitivity of tumor cells to cell death and apoptosis, in addition to preventing migration of tumor cells and cancer metastasis." (PMID 38539447, 2024). "The percentage of GFP-positive cells increased significantly after radiation, while this increase was abrogated in the cells without TRIM21, indicating that SERPINB5-mediated tumor cell radioresistance is dependent on TRIM21." (PMID 32005234, 2020). "The clonogenic survival assay showed that tumor cells lacking SERPINB5 became sensitive and vulnerable to radiation." (PMID 32005234, 2020). "However, in the stromal cells of the tumor buds, LGALS1 was downregulated and candidate genes SERPINB5 and TM4SF4 were upregulated, as compared with the control." (PMID 28687755, 2017). "Among the 17 overexpressed genes, CDX1 (caudal type homeobox 1) had the highest fold difference in tumor versus non-tumor tissues followed by SI (sucrase-isomaltase, aka alpha-glucosidase), KRT16 (keratin 16) and SERPINB5 (serpin peptidase inhibitor, clade B (ovalbumin), member 5)." (PMID 28418924, 2017). "In addition, the candidate genes SERPINB5 (P = 0.008) and TM4SF4 (P = 0.043), which were upregulated in the mesenchymal tumor cells, correlated with a significantly decreased survival potential in patients with higher expression levels." (PMID 28687755, 2017). "Among the 17 upregulated genes, we selected the top five, i.e. CDX1, SI, KRT16, HOXA10, and SERPINB5 for validation using RT-PCR in the 20 pairs of tumor and non-tumor tissues that were not used in RNA-seq." (PMID 28418924, 2017). "A 5-gene PDAC classifier (TMPRSS4, AHNAK2, POSTN, ECT2, SERPINB5) achieved on average 95% sensitivity and 89% specificity in discriminating PDAC from non-tumor samples in four training sets and similar performance (sensitivity = 94%, specificity = 89.6%) in five independent validation datasets." (PMID 26993610, 2016). "Given that BA activation may exert a protective effect on tumors, we hypothesize that elevated SERPINB5 expression in PAAD may indirectly interfere with BA activation and its antitumor function by modulating the local inflammatory environment of the tumor, thus promoting PAAD progression." (PMID 41595468, 2025). "However, interestingly, our study found that SerpinB5 expression level was up-regulated in LUAD, and it may be used as a tumor inducer in the process of tumorigenesis." (PMID 37006240, 2023). "Interestingly, the 5-gene classifier contained only genes labeled related to activated stroma (POSTN) and basal-like tumor (AHNAK2, SERPINB5, TMPRSS4), and excluded classical tumor-like genes, which might explain the inferior classification performance." (PMID 29675033, 2018).
tumor (continued). "The unusual expression of genes like SERPINB5 and S100A2 in differentiated preinvasive cells (and subsequently in tumours) may therefore indicate that a failure to appropriately inactivate stem cell-associated sequences, perhaps by epigenetic modification, is an important proneoplastic mechanism." (PMID 15467767, 2004). "Six loci (CLEC3B (previously TNA), MGP, RASSF1, SDK2, SERPINB5 and XAGE1A (previously GAGED2)) with statistically significantly higher methylation in tumor samples compared with non-tumor samples were identified." (PMID 18947422, 2008).
cancer (54 papers, 2010 to 2025). A tumor composed of atypical neoplastic, often pleomorphic cells that invade other tissues. "Several studies have reported that higher expression of SERPINB5 is associated with poor prognosis and OS in various cancers." (PMID 34938177, 2021). "Promoter hypomethylation induced upregulation of other cancer-associated genes in ovarian cancer includes maspin (SERPINB5), MCJ, and SNCG (synucelin-γ), which encodes an activator of the MAPK and Elk-1 signaling cascades." (PMID 31608277, 2019). "Maspin is a mammary serine protease inhibitor that is encoded by human SERPINB5 gene, and inhibits invasion and metastasis of cancer cells." (PMID 29029529, 2017). "Maspin is a mammary serine protease inhibitor that is encoded by human SERPINB5 gene, and inhibits invasion and metastasis of cancer cells as a tumor suppressor." (PMID 29029529, 2017). "The overall survival rate of the patient with T2 or T3 cancer was positively linked to SERPINB5 mRNA expression (p < 0.05)." (PMID 29029529, 2017). "Only few studies have examined the functional role of rs228952040, and we present additional evidence for a role of SERPINB5 in HCC, as elevated SERPINB5 gene was associated with more aggressive cancers and poorer clinical outcomes." (PMID 27221742, 2016). "SERPINB5 expression has been associated with clinical outcome of several types of human cancers." (PMID 28418924, 2017). "Several studies showed that Maspin (Serpinb5) functions as a tumor suppressor gene, exerting inhibitory effects on angiogenesis, promoting cellular adhesion, and suppressing the migration of cancer cells." (PMID 38539447, 2024). "SERPINB5 has both suppressive and promotive function on cancer progression, according to previous research." (PMID 35800432, 2022). "SERPINB5 has been reported to mediate invasion of cancer cell and identified as an oncogene in multiple tumors." (PMID 35557945, 2022). "Then, accurate scrutiny of hub genes҆ pathways displayed those 3 hub genes (MET, DDIT4, and SERPINB5) were involved in ‘microRNAs in cancer’ pathway, a part of pathways in CRC diseases based on KEGG database." (PMID 34211002, 2021). "Several studies have reported that DNA methylation of the SERPINB5 promoter negatively correlated with gene expression in human cancer and that 5-aza-2′-deoxycytidine treatment is sufficient to restore SERPINB5 expression." (PMID 34588447, 2021). "Among the 84 cancer-related proteins, only serpinB5/maspin expression increased in PC9/ AZDR cells after AZD9291 treatment, suggesting a role in AZD9291 resistance." (PMID 29641535, 2018). "Stage I–IV cancer patients with high SERPINB5 mRNA expression showed a long overall survival time than those with its low expression (p < 0.05), while it was the same for progression-free survival in the patients with stage II and III cancer (p < 0.05)." (PMID 29029529, 2017). "We used TCGA's, Cui's and Cho's datasets to perform bioinformatics analysis, and found that SERPINB5 mRNA expression was lower in gastric normal than cancer tissues, even stratified into intestinal-, diffuse- and mixed-type carcinomas (p < 0.05)." (PMID 29029529, 2017). "According to KM plotter, we found that a higher SERPINB5 expression was positively correlated with overall and progression-free survival rates of all cancer patients, even stratified by aggressive parameters (p < 0.05)." (PMID 29029529, 2017). "Forester's data showed a higher SERPINB5 mRNA expression in intestinal-type than diffuse-type carcinomas (p < 0.05)." (PMID 29029529, 2017). "To confirm that some of these expressions change, we selected several proteins for validation by immunoblotting including Serpinb5 (Pai3), Icam5, Thrombospondin-1 (Thbs1) whose roles are well established in cancer." (PMID 27167202, 2016). "Maspin (SERPINB5) is a tumor suppressor gene that suppresses angiogenesis, enhances the ability of cells to adhere and suppresses cancer cell migration." (PMID 25872784, 2015).
cancer (continued). "As a matter of fact, among clade B serpins, SERPINB3 and SERPINB5 are well studied by various cancer researchers." (PMID 25020046, 2014). "For the prostate dataset, our results show that three genes, namely MAF, ABL1 and SERPINB5, are cancer ones and most other top-ranked genes have a direct interaction with known cancer genes." (PMID 22830977, 2012). "SerpinB5 was expressed in normal breast epithelial cells, skin, prostate, testis, lung, tongue, intestine and thymus, but the expression level was abnormally lower in a variety of malignant tumors compared with the expression level in normal tissue." (PMID 37006240, 2023). "SERPINB5 can promote cancer development by participating in TGFβ and fibrosis regulation." (PMID 36358856, 2022). "Moreover, extracellular matrix remodeling occurs when the expression of SERPINB5 and 7 is reduced, favoring cellular proliferation and migration and, in cases of cancer, invasion and metastasis." (PMID 30944407, 2019). "The candidate genes including BGN, MMP1, LGALS1, SERPINB5, and TM4SF4 probably correlated with cancer development and the EMT program mediated by the integrated pathway of TGFβ/Snail with TNFα/NFκB." (PMID 28687755, 2017). "Under the differentially expressed genes we identified several genes previously related to cancer including the up-regulated SSX1, SSX2, RXFP2, RYR2 and the down-regulated CSTA, TSPAN7, NEO1, S100A, SERPINB5 and SEPP1." (PMID 25857299, 2015). "While expression of ACTA2 – a marker expressed by both myoepithelial cells and cancer-associated fibroblasts (CAFs) – significantly increased in CAS compared to normal stroma, expression of TP63, CHD3, MYH11, SERPINB5 and MME did not increase." (PMID 37391533, 2023). "The tumor suppressor MASPIN (SERPINB5) and SERPINE1 genes showed the highest overexpression, while the most significantly downregulated genes were HIF1A and its target genes, also involved in angiogenesis and metastasis of cancer cells." (PMID 32010430, 2020). "An important JUN target is the SERPINB5 (serpin peptidase inhibitor clade B, member 5), found also up-regulated upon DAC treatment in MCF7, and known as an important suppressor of the invasion and migration of cancer cells." (PMID 25077705, 2014). "This included proteins recently identified as promising therapeutic targets, such as the predominantly cancer cell- rather than stromal cell-expressed PDAC metastasis promoters Agrn, Serpinb5, and Cstb74." (PMID 37156840, 2023).
SERPINB5 also shares sentences with these, for which no sentence is quoted: bladder carcinoma (4 papers); hepatocellular carcinoma (3); non-small cell lung carcinoma (3); adenocarcinoma (2); infection (2); lymphoma (2); nasopharyngeal carcinoma (2); trisomy 18 (2); bladder tumors (1); blast (1); colon carcinoma (1); dysplasia (1); endometrial cancer (1); glioblastoma (1); Hernia (1); intestinal polyp (1); intraductal papillary mucinous neoplasm (1); invasive carcinoma (1); invasive ductal carcinomas of the (1); metabolic disease (1); migraine (1); Oral leukoplakia (1); ovarian adenocarcinoma (1); pemphigus vulgaris (1); polyp (1); scleroderma (1); serous ovarian cancer (1); systemic inflammatory response syndrome (1); T-cell lymphoma (1); thrombosis (1).
A further 2 diseases each share a sentence with SERPINB5 in 1 paper.